CDX2 (caudal type homeobox 2)
Diseases named in the same sentence as CDX2 in open-access papers (continued):
Sharing a sentence is not in itself a finding about the gene and the disease.
colon carcinoma (continued). "Since KLF4 expression is dependent on CDX2 in human colon cancer cells, our finding is consistent with these reports and suggests that KLF4 regulates cell polarity through multiple genes, including LKB1." (PMID 22384261, 2012). "We further provide data supporting parallel correlation between claudin-1 and Cdx2 expression in colon cancer patient samples." (PMID 22719836, 2012). "We also generated a polyclonal population of SW480 (colon cancer cell line) cells expressing high levels of CDX2 by infection of the cells with replication-defective retroviruses carrying a full-length human CDX2 cDNA." (PMID 23133598, 2012). "In this study, CK-20 and CDX-2 were used as markers for determining the lymphatic and hepatic metastases with a colon carcinoma primary." (PMID 22164281, 2011). "CD26 mRNA and protein levels increase in a confluence-dependent manner in colon carcinoma cell lines, with c-Myc acting as a repressor and Cdx2 acting as an enhancer of CD26 expression." (PMID 21284881, 2011). "On the other hand, it was shown that CDX2 enhances proliferation and has tumorigenic potential in the human colon cancer cell lines LoVo and SW48 used in this study." (PMID 19781065, 2009). "Second, our data add to untangle the complex and conflicting biological functions of CDX2 in colon cancer." (PMID 19781065, 2009). "In colon cancer cells CDX2 expression was initially reported to be reduced compared to normal colonic mucosa with an inverse relationship between CDX2 expression and advanced stages of cancers." (PMID 19781065, 2009). "The CDX2 transcription factor is expressed in intestinal epithelium and is markedly down-regulated in colon tumours." (PMID 11161380, 2001). "Blockage of NUPR1 might be as a potential therapeutic strategy for stage II-III CDX2-positive colon cancer." (PMID 41820294, 2026). "Genetic or pharmacological blockage of CDX2-NUPR1 axis may strengthen the anticancer efficacy of adjuvant chemotherapy on stage II-III CDX2-positive colon cancer in vitro and in vivo." (PMID 41820294, 2026). "Blockage of NUPR1 might be as a potential therapeutic strategy for CDX2-positive stage II-III colon cancer." (PMID 41820294, 2026). "The complete loss of Cdx1 resulted in extensive invasion of the small-intestinal tumor cells, whereas the absence of Cdx1 in conjugation with a heterozygous Cdx2 mutation led to the invasion of the colonic tumor cells." (PMID 40399276, 2025). "Previous data showed that CDX2 levels were reduced in human colon cancer tissues." (PMID 40399276, 2025). "Although no invasion was observed in case of Apc+/−Cdx1+/− colonic tumors, an additional Cdx2 mutation induced submucosal invasion." (PMID 40399276, 2025). "For example, various types of microRNAs and long non-coding RNAs in blood or stool samples have been significantly correlated with colon cancer, and some tissue biomarkers (including caudal type homeobox 2, special AT-rich sequence-binding protein 2, and glycoprotein A33) have been identified." (PMID 38366023, 2024). "Interestingly, normal BLM and Min colon epithelium exhibited the same level of CDX2 protein whereas the level of CDX2 protein drastically decreased in Min colon tumors." (PMID 38893159, 2024). "Besides evaluating the intensity pattern of CDX2 in each of the 43 colon tumors analyzed in this study, we also measured the proportion of regions containing CDX2-stained (positive and moderate) and unstained nuclei relative to the total tumor area." (PMID 38786321, 2024). "The noninvasive methodology might be useful for colon cancer models, e.g., CDX2, villin, and APC expression-based models, which often are used in long-term experiments, with few options for noninvasive monitoring of early tumor development." (PMID 37962942, 2024).
colon carcinoma (continued). "In this study, we conducted an immunohistochemical assessment of CDX2 expression on a cohort of 43 intraoperatively obtained tumor specimens from patients diagnosed with colon cancer at Colțea Clinical Hospital in Bucharest, between April 2019 and December 2023." (PMID 38786321, 2024). "KRAS and NRAS mutations were observed exclusively in non-CDX2-suppressed colon cancers, with no cases in the CDX2-suppressed group bearing such mutations." (PMID 39452477, 2024). "Our study evaluates the impact of CDX2 expression on colon cancer pathology, noting that most immunohistochemical scoring system models may not fully capture tumor heterogeneity." (PMID 38786321, 2024). "Moreover, our novel immunohistochemical scoring system reveals a distinct subset of colon tumors exhibiting reserved prognostic outcomes, distinguished by their “mosaic” CDX2 expression pattern." (PMID 38786321, 2024). "Recently, Dalerba and colleagues demonstrated that without adjuvant chemotherapy, CDX2‐negative tumors were associated with a low 5‐year DFS rate among colon cancer patients." (PMID 37602699, 2023). "In this study, we explored the expression of prognostic markers in patients with pT3 and pT4 colon cancers including HLA-G and PD-L1, two markers of immune evasion, as well as the expression of CDX2, a marker of differentiation, and CD3 and CD8, markers of TILs." (PMID 35027037, 2022). "Additionally, the combination of OCA plus GSK126 synergistically elevated CDX2 expression in colon cancer cells and their derived xenograft tumor, compared to the single drug." (PMID 35449124, 2022). "Overexpression of CDX2 reduced colon cancer formation in mice." (PMID 35055034, 2022). "CDX2, known as a nuclear transcription factor, plays important roles in regulating the epithelial to mesenchymal transition, and acts as a prognostic factor and emerging biomarker in colon cancer." (PMID 36712870, 2022). "The Caudal-type homeobox transcription factor 2 (CDX2) gene is documented as a prognostic biomarker of colon cancer with high value in mesenchymal (MS4) molecular subgroup and a tumorigenic role by promotion of anchorage-independent cell growth and anoikis resistance." (PMID 35340411, 2022). "In an in vitro study, CDX2 knockdown promoted the proliferation of colon cancer cells." (PMID 35328309, 2022). "Traditionally used in identifying cancers of unknown origin, CDX2 has recently been identified as an emerging prognostic biomarker in colon cancer." (PMID 35323316, 2022). "A sporadic colon tumor model was generated by crossing the known, adenomatous polyposis coli model, Apcfl/fl mice, or double Apcfl/fl;Atg5fl/fl mice to a tamoxifen-inducible colon–specific Cdx2-ERT2Cre." (PMID 34138755, 2021). "In fact, Cdx2 expression has been shown to be lower in colon carcinoma with the highest grades." (PMID 32426274, 2020). "Furthermore, CDX2, which is the marker of colon cancer cells, were down regulated in cGAMP treated group by immunohistochemistry staining." (PMID 32596152, 2020). "LTC4-induced 15-PGDH downregulated Wnt target genes in a GLI1-dependent manner with concurrent activation of the intestinal tumour suppressor CDX2, which positively regulates the expression of SI in colon cancer cells and is a prominent intestinal differentiation marker." (PMID 32814764, 2020). "The results of this study may help to elucidate the pro-metastatic mechanisms in the perioperative phase and the role of CDX2 in colon cancer metastasis." (PMID 32408894, 2020). "Furthermore, CDX2 has been shown to mediate E-selectin ligand expression in colon cancer cells, a crucial component in the attachment of cancer cells to distant tissues during metastasis." (PMID 32408894, 2020). "Lack of CDX2 expression in colon cancer cells is associated with aggressive clinical behaviour and can be used as an adverse prognostic biomarker." (PMID 32408894, 2020).
colon carcinoma (continued). "Furthermore, loss of CDX 1 and/or CDX2 was shown to impact TGF beta signaling and tumor invasion in murine APC mutant colon cancer models." (PMID 30909444, 2019). "CDX2 is used to predict the benefit of adjuvant chemotherapy in colon cancer patients." (PMID 31596728, 2019). "In summary, our study demonstrates that CDX2 inhibits the proliferation and tumor formation of colon cancer cells by suppressing Wnt signaling activity and reveals a molecular mechanism by which CDX2 regulates the transcriptional activation of GSK-3β and Axin2." (PMID 30631044, 2019). "Overall, our results suggest a molecular sub-cluster of colon cancer cells with low CDX2 and VDR expression is sensitive to chemotherapy, BRAF inhibitors and PI3K-mTOR inhibitors treatment and provide an example of translation of cancer classification to subgroup guided therapies." (PMID 31596728, 2019). "Our study aimed to determine whether CDX2 suppressed Wnt signaling in colon cancer cells by regulating these genes." (PMID 30631044, 2019). "In addition, suppression of Wnt signaling by XAV-939 abolished the growth and viability of colon cancer cells induced by CDX2 knockdown." (PMID 30631044, 2019). "Based on those results and previous published data, we speculated that genes with similar expression profiling of CDX2 were also important prognostic biomarkers for colon cancer patients." (PMID 31596728, 2019). "However, an intestinal CDX2 knockout cell line was recently constructed using the LS174T colon cancer cell line." (PMID 31216773, 2019). "CDX2 could suppress intestinal cancer development and is a critical biomarker in colon cancer prognosis." (PMID 31596728, 2019). "We then determined the expression of CDX2 in different colon cancer sub-clusters." (PMID 31596728, 2019). "CDX2 functions as a tumor suppressor gene that maintains the intestinal epithelium, adhesion, proliferation, and apoptosis and its expression levels are reduced in most human colon cancer tissues." (PMID 31783700, 2019). "Coskun reported that in colon cancer cells, CDX2 suppressed the Wnt signaling activity." (PMID 30631044, 2019). "Moreover, there is a positive correlation between VDR and CDX2 expression in primary colon cancer patients." (PMID 31596728, 2019). "In addition, downregulation of CDX2 leads to development of intestinal neoplasia and is introduced as a prognostic marker for colon cancer." (PMID 31090196, 2019). "Our study showed that CDX2 knockdown promoted cell proliferation in vitro, accelerated tumor formation in vivo, and induced the G1/S cell cycle transition, whereas overexpression of CDX2 suppressed cell proliferation, suggesting that CDX2 inhibits proliferation in colon cancer cells." (PMID 30631044, 2019). "Previous studies have reported that CDX2-negative colon cancer is associated with poor prognostic factors such as advanced stage, poorly differentiated cancer, vascular invasion, BRAF mutation, and CIMP positive status." (PMID 30785889, 2019). "Moreover, studies have demonstrated that overexpression of CDX2 has an inhibitory effect on colon cancer growth in in vitro experiments and in tumor-transplantation studies performed in mice." (PMID 30087389, 2018). "Moreover, CDX2 acts as a tumor suppressor, and inhibition of CDX2 expression increases the invasiveness of colon cancer." (PMID 27755609, 2016). "Indeed, RELA/p65, the subunit of the key inflammatory transcription factor NFKB/NF-κB, is claimed one of the regulators of CDX2 in colon cancer cells." (PMID 26910375, 2016). "Additionally, positive immunostaining for CDX2 is a highly specific and sensitive marker for colon carcinoma." (PMID 25883818, 2015). "In the present study, the effects of the overexpression of CDX2 on the growth of colon cancer was were investigated via subcutaneous implantation of CDX2-overexpressing LoVo colon cancer cells, delivered using a transfected eukaryotic expression vector, pEGFP-C1-CDX2, into a nude mouse model." (PMID 26005051, 2015).
colon carcinoma (continued). "The present study aimed to examine the inhibitory effects of the overexpression of CDX2 on subcutaneously-transplanted tumors, derived from LoVo colon cancer cells, in nude mice, and to provide experimental evidence for the biotherapy of colon cancer." (PMID 26005051, 2015). "Minoo's study of 399 CRCs showed that TOPK could be a marker of tumor in colon cancer in combination with CDX2, CD44v6, CD44s, nuclear ß-catenin, pERK, APAF-1, E-cadherin, p21, and bcl2." (PMID 25881543, 2015). "Interestingly, it was previously demonstrated that Sox21 is induced by Sox2, and, unlike Sox2, Sox21 negatively regulates transcription of Cdx2 in mES and colon cancer cells." (PMID 26783396, 2015). "Therefore, forced overexpression of CDX2 under a cytomegalovirus (CMV) promoter in colon cancer cells is used to inhibit LoVo colon cancer cell invasion and gastric cancer progression." (PMID 25847407, 2015). "Because in intestinal metaplasia of the stomach, CDX2 and Reg IV expression are well correlated, the use of a colon cancer cell line might be suitable for the model of intestinal metaplasia." (PMID 23133598, 2012). "However, immunohistochemical analysis has detected strong Cdx2 expression in ∼90% of the human colon cancer samples." (PMID 22719836, 2012). "Together, above findings would suggest function of Cdx2 as a colon tumor suppressor." (PMID 22719836, 2012). "Also, in colon cancer patient samples, we observed a significant and parallel correlation between claudin-1 and Cdx2 expressions." (PMID 22719836, 2012). "Therefore, we investigated a possible correlation between Cdx2 and claudin-1 expressions in colon cancer." (PMID 22719836, 2012). "Importantly, further analysis demonstrated a significant correlation (p<0.01) between claudin-1 and Cdx2 expressions in 36∶50 (72%) colon cancer samples." (PMID 22719836, 2012). "Taken together, it can be postulated that the role of Cdx2 in the regulation of colon cancer may depend upon the differentiation status of the colon cancer cells and interaction with other transcription factors." (PMID 22719836, 2012). "Upon scanning endogenous Cdx2 expression levels in cell lines, we found that HepG2 liver carcinoma cells express very low Cdx2 levels compared to the Caco2 colon cancer line or mouse colon; though the gene was expressed about 10-fold above the negative background seen in liver." (PMID 21935353, 2011). "Type I collagen has previously been shown to reduce cdx-2 expression in colon cancer cells." (PMID 19568234, 2009). "Moreover, they link CDX2 to EGF-mediated cancer cell proliferation, migration and invasion, and provide a basis to further dissect the role of CDX2 in colon cancer progression." (PMID 19781065, 2009). "Similarly, higher proliferation rates were observed in the small-intestinal tumor organoids derived from cis-Apc+/−Cdx1+/− mice and in colonic tumor organoids derived from cis-Apc+/−Cdx1+/− and Cdx2+/−-cis-Apc+/−Cdx1+/− mice than in those derived from Apc+/− mice." (PMID 40399276, 2025). "Moreover, it was shown that the inactivation of HNF4α in colon cancer cells and conditionally knockout mice decreased the expression of the gut-specific homeotic TF Cdx2, suggesting their positive correlation and tumor suppressive activity of HNF4α in colon cancer." (PMID 38372868, 2024). "Additionally, the inclusion criteria favoring tumors with higher invasion grades (pT3 and pT4) may not accurately reflect the behavior and prognostic implications of CDX2 expression in earlier stages of colon cancer." (PMID 38786321, 2024).
colon carcinoma (continued). "However, high grade, mucinous and/or mismatch repair deficient colonic adenocarcinomas are associated with negative CDX2 expression, which is a prognostic factor of colon cancer without metastatic lesions." (PMID 32867793, 2020). "This indicates that the absence of CDX2 expression results in reduced cancer cell adherence, and that fluctuation of CDX2 levels in cancer cells could be important in the metastatic process of colon cancer cells." (PMID 32408894, 2020). "However, to the best of our knowledge, the precise mechanisms of the CDX2-mediated inhibition of colon cancer cell proliferation have not been proved to be associated with its suppression of Wnt signaling." (PMID 30631044, 2019). "However, whether CDX2 inhibits the proliferation and tumor formation of colon cancer cells by suppressing the activity of the Wnt signaling was not fully addressed." (PMID 30631044, 2019). "Therefore, weak and scattered positivity might be overlooked if strong and homogeneous CDX2 expression in colon cancer is used as a control." (PMID 24489794, 2014). "Thus, a tumor-promoting role of Cdx2 in colon cancer can be envisaged." (PMID 22719836, 2012). "K7 and TTF‐1 are the most sensitive and specific markers for identifying lung adenocarcinoma, while CDX2 and SATB2 are the most sensitive and specific markers for identifying colon cancer." (PMID 40309045, 2026). "While CK7 and CK20, markers of cholangiocarcinoma epithelium, showed focal positivity, CDX-2 and CK20, which are expressed in colon cancer, also showed positivity." (PMID 40755904, 2025). "Colon-origin tumors are PSA-negative, CDX2- and CEA-positive or nuclear β-linker-positive and can also be differentiated by combining clinical data with a history of colon cancer or endoscopy." (PMID 40896436, 2025). "Through the use of in vitro and in vivo experiments as well as a collection of samples from CRC patients, researchers were able to determine that CDX2 is a significant inhibitor of the invasion phenotype and EMT in colon cancer." (PMID 36277982, 2022). "CDX2 status, EGFR status, tumour size, tumour location and lymph node ratio (LNR) were ranked of lowest importance in determining prognosis in colon cancer." (PMID 35323316, 2022). "CDX2 status, tumour location, tumour size, TILs, KRAS and BRAF status were ranked of lowest importance in determining prognosis in colon cancer." (PMID 35323316, 2022). "In conclusion, we investigated HLA-G, PD-L1, CDX2, and CD3 and CD8 as prognostic markers in patients with pT3 and pT4 colon cancers." (PMID 35027037, 2022). "Consistent with our findings, previous studies reported that Reg IV expression was induced by CDX2 overexpression in OMC-3 ovarian mucinous carcinoma cells and HT-29 colon cancer cells and suppressed by CDX2 siRNAs in HSC-39 gastric cancer cells." (PMID 33639844, 2021). "In this study, by conducting in vitro and in vivo assays and using a group of CRC patients, we first showed that CDX2 is a major inhibitor of the invasion-prone phenotype and EMT in colon cancer cells." (PMID 33239678, 2021). "To further determine the role of PTEN in CDX2-inhibited Akt phosphorylation and invasion of colon cancer cells, we ectopically expressed or knocked down PTEN in colon cancer cells with stable CDX2 knockdown or overexpression." (PMID 33239678, 2021). "In fact, the overexpression of the caudal-related homeobox transcription factor (Cdx2) has been reported to upregulate the expression of ABCB1/gene and consequently P-glycoprotein in highly resistant colon carcinoma to chemotherapy." (PMID 32426274, 2020). "As the circulating colon cancer cells establish metastasis they undergo mesenchyme-to-epithelia transition (MET) and CDX2 expression is re-established, allowing for it to be used as a marker to determine the primary tumours colonic origin." (PMID 32408894, 2020).